DONSON (DNA replication fork stabilization factor DONSON)
Description:
Replisome component that maintains genome stability by protecting stalled or damaged replication forks. After the induction of replication stress, required for the stabilization of stalled replication forks, the efficient activation of the intra-S-phase and G/2M cell-cycle checkpoints and the maintenance of genome stability.
Synonyms: C21orf60; B17; C2TA; DKFZP434M035; MGORS10; MIMIS; MISSLA
Tractability: PROTAC: ubiquitination databases record sites on it.
Gene: Protein-coding gene on chromosome 21 (33,559,542 to 33,589,015, reverse strand). Ensembl gene ENSG00000159147.
Subcellular location: Nucleus
Subcellular location (Human Protein Atlas): Cell Junctions; Nucleoplasm; Cytosol
Gene Ontology:
Molecular function: protein binding
Biological process: DNA damage checkpoint signaling; DNA replication; mitotic DNA replication checkpoint signaling; mitotic G2 DNA damage checkpoint signaling; replication fork processing; nuclear DNA replication
Cellular component: nucleus; replication fork; replisome
Genetic constraint (gnomAD): Loss-of-function variants: 40 observed, 56.71 expected, observed/expected ratio (o/e) 0.71, 90% interval 0.55 to 0.92. The upper end of that interval is the gene's LOEUF score, 0.92, which puts it in group 3 of 6, group 1 being the genes least tolerant of losing a copy. Missense variants: 676 observed, 627.32 expected, observed/expected ratio (o/e) 1.08, 90% interval 1.01 to 1.15. Synonymous variants: 252 observed, 228.96 expected, observed/expected ratio (o/e) 1.1, 90% interval 0.99 to 1.22.
Homologues: Orthologues: chimpanzee DONSON (99% identical), macaque DONSON (96% identical), rabbit DONSON (86% identical), dog DONSON (84% identical), pig DONSON (83% identical), guinea pig DONSON (80% identical), mouse Donson (77% identical), rat Donson (77% identical), tropical clawed frog donson (60% identical), Drosophila melanogaster hd (29% identical), Caenorhabditis elegans dnsn-1 (20% identical).
Diseases named in the same sentence as DONSON in open-access papers:
DONSON is named in the same sentence as 25 diseases in open-access papers, as found by Europe PMC text mining. Sharing a sentence is not in itself a finding about the gene and the disease. The quoted sentences say what the papers report.
microcephaly (11 papers, 2017 to 2025). A congenital or acquired developmental disorder in which the circumference of the head is smaller than normal for the person's age and sex. "Biallelic hypomorphic DONSON variants have previously been found to underlie a clinically distinct primordial dwarfism of severely disproportionate microcephaly and variable skeletal abnormalities mainly present in the upper limb (MISSLA; MIM 617604)." (PMID 37059840, 2023). "Biallelic mutations in DONSON, an essential gene encoding for a replication fork protection factor, were linked to skeletal abnormalities and microcephaly." (PMID 33739968, 2021). "Variants in DONSON have previously been associated with extreme microcephaly, short stature and limb anomalies and perinatal lethal microcephaly-micromelia syndrome." (PMID 31784481, 2020). "Here, we present a noncoding mutation in DONSON as the cause of microcephaly-micromelia syndrome and link DONSON to the key complexes mediating genome replication that are disrupted in other microcephalic primordial dwarfism syndromes." (PMID 28630177, 2017). "Loss of DONSON function in early neocortical progenitor cells is consistent with the profound microcephaly and brain malformations of MMS." (PMID 28630177, 2017). "DONSON mutations are also associated with other microcephalic dwarfism disorders (microcephaly, short stature, and limb abnormalities, and microcephaly-micromelia syndrome), where brain size is disproportionately affected, and limb reduction abnormalities are evident." (PMID 37590370, 2023). "Our findings help explain why the neocortex is most severely affected in individuals with DONSON mutations and suggest that DONSON-dependent microcephaly might be associated with so far unrecognized defects in cortical GABAergic neurons." (PMID 33739968, 2021). "Subsequent studies linked DONSON mutations to micromelia syndrome, Meier-Gorlin syndrome, Seckel-like syndrome, Femoral Facial syndrome, and microcephaly, short stature and limb abnormalities, which are all characterized by microcephaly as well as skeletal and craniofacial abnormalities." (PMID 33739968, 2021). "Similarly, the use of transcriptomics, such as RNA-seq, may expedite our identification of non-coding variants in patients; the use of transcriptomics in a patient with microcephaly-micromelia syndrome found a non-coding mutation in DONSON that caused aberrant splicing." (PMID 33178111, 2020). "Because MMS has a severe microcephaly phenotype, we assessed DONSON expression in greater detail in human and mouse embryonic and fetal brains." (PMID 28630177, 2017). "The emerging role of DONSON in microcephaly and its strong expression in the telencephalic proliferation zones prompted us to test whether pallial progenitors require Donson function." (PMID 33739968, 2021). "Recent findings suggest that biallelic mutations in DONSON, a replication fork stabilization factor, cause microcephaly and skeletal defects, but this has not been formally tested." (PMID 33739968, 2021).
gastric cancer (7 papers, 2021 to 2025). A primary or metastatic malignant neoplasm involving the stomach. "The expression of miR-30a-3p inhibits small cell lung cancer cell proliferation, induces cell cycle arrest, and apoptosis, potentially through targeting DONSON, and regulates gastric cancer cell proliferation by targeting MAD2L1." (PMID 41361055, 2025). "A previous study showed that circ-DONSON interacts with the RBP–nucleosome remodelling factor (NURF) complex by directly combining with the SNF2L subunit in gastric cancer." (PMID 35366893, 2022). "Circ-DONSON promotes gastric cancer cell growth and invasion via NURF complex dependent activation of SRY-box transcription factor 4 (SOX4)." (PMID 34853591, 2021). "Similarly, in gastric cancer (GC), circ-DONSON recruits the NURF complex to the SOX4 promoter and initiates its transcription, thus promoting the proliferation, migration, and invasion of GC cells." (PMID 35645336, 2022). "Circ-DONSON is involved in the progression of glioma and gastric cancer." (PMID 34853591, 2021). "Additionally, circ-DONSON might recruit the NURF complex to transcription factor SOX4 promoter and initiate its transcription, thus facilitating gastric cancer growth and invasion." (PMID 34116677, 2021). "For instance, an interesting study reveals that silencing of circ-DONSON (circbase ID: hsa_circ_0004339) represses cell proliferation, migration, and invasion, and enhances apoptosis via recruiting the nucleosome remodeling factor (NURF) complex to initiate SOX4 expression in gastric cancer." (PMID 33729388, 2021).
microcephalic primordial dwarfism (4 papers, 2020 to 2023). Primordial dwarfism with microcephaly. "Mutations in DONSON lead to microcephalic primordial dwarfism (MPD), which is a collective term for a group of human disorders characterised by intra-uterine and postnatal growth delay alongside marked microcephaly." (PMID 37638758, 2023). "We also mapped known patient mutations causing microcephalic primordial dwarfism (MPD), specifically Meier-Gorlin syndrome in humans, onto the model structure of human DONSON." (PMID 37638758, 2023).
primordial dwarfism (3 papers, 2023). "As primordial dwarfism is often associated with mutations in proteins involved in replication initiation, our findings support a role for DONSON dimerization in origin activation." (PMID 37820732, 2023). "Mutations in DONSON have been known for a while to be the underlying genetic problems, which lead to microcephalic primordial dwarfism (MPD)." (PMID 37638758, 2023). "Collectively, our data provide a link between primordial dwarfism, DONSON’s homodimerization and the ability to incorporate GINS into the CMG helicase, in a key step on the path to replication initiation." (PMID 37820732, 2023). "DONSON reconfigures the MCM motors in the double CMG, and primordial dwarfism patients’ mutations disrupting DONSON dimerization affect GINS and MCM engagement in human cells and DNA synthesis in Xenopus egg extracts." (PMID 37820732, 2023).
clear cell renal carcinoma (2 papers, 2020 to 2023). A malignant epithelial neoplasm of the kidney characterized by the presence of lipid-containing clear cells within a vascular network. "DONSON was found to be a biomarker for risk stratification in clear cell renal carcinoma (ccRCC), and in prostate carcinoma (PCa)." (PMID 37638758, 2023). "Thus, DONSON was found to be a robust biomarker for risk stratification in clear cell renal cell carcinoma (ccRCC), and in vitro, DONSON was linked to a malignant phenotype in ccRCC cell culture models." (PMID 33228112, 2020). "Of note, the DONSON protein was localized in the cytoplasm of the PCa samples, which was in accordance with the staining pattern observed in The Human Protein Atlas and for clear cell renal cell carcinoma tissue." (PMID 33228112, 2020).
glioma (2 papers, 2020 to 2021). A benign or malignant brain and spinal cord tumor that arises from glial cells (astrocytes, oligodendrocytes, ependymal cells). "Circ-DONSON has been reported to be highly expressed in glioma tissues and promote cell proliferation and migration through modulating FOXO3." (PMID 34853591, 2021).
Meier-Gorlin syndrome (2 papers, 2020 to 2023). "Mutations in DONSON have recently been shown to lead to the Meier-Gorlin syndrome; this novel replication initiation role of DONSON therefore provides the explanation for the phenotypes caused by DONSON mutations in patients." (PMID 37638758, 2023). "To test the effect of DONSON disease-causing mutations on replication initiation, we cloned and purified a selection of DONSON point mutations that were reported to cause MPD or Meier-Gorlin syndrome in humans." (PMID 37638758, 2023). "Interestingly, mutations in DONSON were also recently shown to specifically cause Meier-Gorlin syndrome, the subtype of MPD caused by dysregulation of DNA origin firing and replication initiation." (PMID 37638758, 2023).
prostate carcinoma (2 papers, 2020 to 2023). A carcinoma that arises from epithelial cells of the prostate gland. "We identified DONSON to be associated with an aggressive histopathological phenotype and unfavorable survival in prostate cancer (PCa) in different transcriptomic cohorts and on the protein level in our tissue microarray cohort." (PMID 33228112, 2020). "Downstream neighbor of Son (DONSON) plays a crucial role in cell cycle progression and in maintaining genomic stability, but its role in prostate cancer (PCa) development and progression is still underinvestigated." (PMID 33228112, 2020).
dwarfism (1 paper, 2023). "Here, we report that DONSON, a metazoan protein mutated in microcephalic primordial dwarfism, is required for CMG assembly in vertebrates." (PMID 37590370, 2023).
metastatic cancer (1 paper, 2023). A carcinoma which has spread from the original site of growth to another anatomic site. "Overexpression of DONSON was detected in primary and metastatic cancer lesions." (PMID 36345848, 2023).
cancer (8 papers, 2015 to 2024). A tumor composed of atypical neoplastic, often pleomorphic cells that invade other tissues. "Of note, in a comprehensive pan-cancer analysis of 30 distinct tumor entities using TCGA datasets, we recently found DONSON overexpression to be associated with unfavorable overall survival in diverse entities, suggesting tumor-independent oncogenic properties of this largely unknown gene." (PMID 33228112, 2020). "Among the putative target genes regulated by miR‐30a‐3p, we focused on DONSON because our previous study showed that its aberrant expression enhanced cancer cell aggressive phenotypes in RCC cells." (PMID 36345848, 2023). "Aberrant expression of DONSON enhances the malignant features of cancer cells, and its overexpression is a strong independent predictor of unfavorable overall survival in patients with RCC." (PMID 36345848, 2023). "DONSON was associated with an aggressive phenotype in the PCa TCGA cohort, two GEO PCa cohorts, and our PCa TMA cohort as DONSON expression was particularly strong in locally advanced, metastasized, and dedifferentiated carcinomas." (PMID 33228112, 2020). "DONSON expression in the primary tumor was particularly strong in locally advanced, metastasized, and dedifferentiated carcinomas (TNM Stage, Gleason)." (PMID 33228112, 2020). "Since the PCa TCGA dataset set only contains the expression profiles of primary carcinomas, we wanted to investigate further data sets to more precisely examine the role of DONSON during tumor progression." (PMID 33228112, 2020). "Given that DONSON is overexpressed in advanced dedifferentiated carcinomas, the gene might also be targeted for therapeutic purposes." (PMID 33739968, 2021). "In addition, the proliferative activity measured by Ki67 expression, which is also an established prognostic biomarker in PCa and other cancers, was significantly correlated with DONSON expression, which seems comprehensible due to the predicted function of DONSON as part of the replisome." (PMID 33228112, 2020). "A small number of genes specific for cancer at baseline were downregulated in APG-treated cancer patients after 3h and 24h (ACVR2B, CACNA1F, DONSON, PIH1D3, PRDM6)." (PMID 35600369, 2022). "Some genes always selected by each method were found (COPS7B, DONSON, GTF2E2, HAUS8, PRH2, and ZNF18) with known roles in cancer formation and progression." (PMID 35954157, 2022). "Interestingly, the PCa TMA cohort showed a heterogeneous picture, with some tumors being DONSON-negative while others, especially Gleason 8 and higher carcinomas, strongly overexpressed DONSON." (PMID 33228112, 2020).
tumor (4 papers, 2019 to 2024). "In vitro, specific DONSON-knockdown significantly reduced the migration capacity in the PCa cell lines PC-3 and LNCaP, which further suggests a tumor-promoting role of DONSON in PCa." (PMID 33228112, 2020). "In vitro, specific DONSON-knockdown significantly reduced the migration capacity in PC-3 and LNCaP, which further suggests a tumor-promoting role of DONSON in PCa." (PMID 33228112, 2020). "We also found that circ-DONSON overexpression predicted advanced tumor stage, metastasis and poor prognosis." (PMID 30922402, 2019). "Therefore, we think that our study on DONSON in PCa, as well as the fact that DONSON overexpression seems to mediate tumor-independent oncogenic properties, could be a starting point for further basic and oncological research on DONSON." (PMID 33228112, 2020).
DONSON also shares sentences with these, for which no sentence is quoted: breast carcinoma (2 papers); Seckel syndrome (2); brain malformations (1); colorectal cancer (1); COVID-19 (1); developmental delay (1); Fanconi anemia (1); femoral-facial syndrome (1); Gorlin syndrome (1); liver cancer (1); Macrocephaly (1); renal cell carcinoma (1); small cell lung carcinoma (1).